SPDYE3 (speedy/RINGO cell cycle regulator family member E3)
Synonyms: SPDYB2
Tractability: No criterion of Open Targets' tractability assessment is met for any kind of drug.
Gene: Protein-coding gene on chromosome 7 (100,307,702 to 100,322,372, forward strand). Ensembl gene ENSG00000214300.
Gene Ontology:
Molecular function: protein kinase binding
Genetic constraint (gnomAD): Loss-of-function variants: 14 observed, 28.55 expected, observed/expected ratio (o/e) 0.49, 90% interval 0.32 to 0.77. The synonymous counts are far from expectation, so gnomAD's model fits this gene poorly and the ratio says little. Missense variants: 216 observed, 298.36 expected, observed/expected ratio (o/e) 0.72, 90% interval 0.65 to 0.81. Synonymous variants: 84 observed, 112.23 expected, observed/expected ratio (o/e) 0.75, 90% interval 0.63 to 0.9.
Homologues: Orthologues: rat Spdye4 (25% identical), mouse Spdye4a (24% identical), mouse Spdye4b (22% identical). Paralogues in human: SPDYE18 (46% identical), SPDYE16 (46% identical), SPDYE5 (46% identical), SPDYE6 (46% identical), SPDYE2 (45% identical), SPDYE2B (45% identical), SPDYE21 (45% identical), SPDYE1 (45% identical), SPDYE12 (43% identical), SPDYE10 (43% identical), SPDYE11 (43% identical), SPDYE17 (43% identical), and 6 more.
Diseases named in the same sentence as SPDYE3 in open-access papers:
SPDYE3 is named in the same sentence as 1 disease in open-access papers, as found by Europe PMC text mining. Sharing a sentence is not in itself a finding about the gene and the disease.
SPDYE3 shares sentences with these, for which no sentence is quoted: cancer (1 paper).